RNF222 (ring finger protein 222)
Tractability: Antibody: UniProt predicts a signal peptide or a membrane-spanning region.
Gene: Protein-coding gene on chromosome 17 (8,390,702 to 8,397,827, reverse strand). Ensembl gene ENSG00000189051.
Subcellular location: Membrane
Gene Ontology:
Cellular component: membrane
Genetic constraint (gnomAD): Loss-of-function variants: 16 observed, 11.07 expected, observed/expected ratio (o/e) 1.45, 90% interval 0.96 to 1.91. The upper end of that interval is the gene's LOEUF score, 1.91, which puts it in group 6 of 6, group 1 being the genes least tolerant of losing a copy. Missense variants: 298 observed, 266.73 expected, observed/expected ratio (o/e) 1.12, 90% interval 1.02 to 1.23. Synonymous variants: 141 observed, 125.54 expected, observed/expected ratio (o/e) 1.12, 90% interval 0.98 to 1.29.
Homologues: Orthologues: chimpanzee RNF222 (99% identical), macaque RNF222 (97% identical), rabbit RNF222 (93% identical), guinea pig RNF222 (87% identical), rat Rnf222 (85% identical), mouse Rnf222 (84% identical), pig RNF222 (82% identical), dog RNF222 (80% identical), tropical clawed frog rnf222 (35% identical).
Diseases named in the same sentence as RNF222 in open-access papers:
RNF222 is named in the same sentence as 5 diseases in open-access papers, as found by Europe PMC text mining. Sharing a sentence is not in itself a finding about the gene and the disease. The quoted sentences say what the papers report.
Moyamoya disease (1 paper, 2021). Moyamoya disease (MMD) is a rare intracranial arteriopathy involving progressive stenosis of the cerebral vasculature located at the base of the brain causing transient ischemic attacks or strokes. "The physiologic role of Rnf222 has not been described currently; however, other members of the ring finger protein family have been associated with cerebral vascular diseases like Moyamoya disease and atherosclerotic stroke." (PMID 34440888, 2021).
Obesity (1 paper, 2020). Accumulation of substantial excess body fat. "These genes were also examined in female placentae, however, only Pi15, Nup210, Acta2, Rnf222, and Muc15 were significantly modulated by obesity." (PMID 32203108, 2020).
RNF222 also shares sentences with these, for which no sentence is quoted: cervical adenocarcinoma (1 paper); cervical cancer (1); cervical squamous cell carcinoma (1).